CD4 (CD4 molecule)
Diseases named in the same sentence as CD4 in open-access papers (continued):
Sharing a sentence is not in itself a finding about the gene and the disease.
infection (continued). "Furthermore, infection of activated primary human CD4+ T cells also showed a requirement of Vpu in BST2 down regulation and efficient production of infectious virus." (PMID 24195843, 2013). "However, CD4+ T cells are unlikely to be the target cell since SIV- and SHIV-infected macaques resulted in CD4+ T cell depletion at the end stage of infection." (PMID 23885255, 2013). "We also tested the effect of Slit2N on infection of resting CD4+ T-cells." (PMID 23294842, 2013). "In comparison to healthy controls, CD4+ T cell percentages were substantially reduced in the blood of all but one of the SIV infected macaques by 2 weeks post-infection (p.i.)and were depleted with statistical significance for the entire group (p<0.05) at necropsy." (PMID 24312248, 2013). "Moreover, one animal demonstrated a steep drop in CD4+ T cell counts, persistent but low viremia, and opportunistic infections after three years of infection (unpublished observations)." (PMID 23825473, 2013). "Consequently, blocking of ICAM-1-LFA-1 interactions between mDC and non-activated primary CD4+ T cells substantially reduced the productive mDC-mediated HIV-1 trans-infection of CD4+ T cells." (PMID 23590845, 2013). "However, little is known about the early characteristics and kinetics of the virus’ systemic dissemination in patients, specifically its distribution among the various CD4 cell subsets within the first month post-infection." (PMID 23691172, 2013). "This suggests low viral replication to lead to low rate of infection of CD4+ T cells." (PMID 23696852, 2013). "CD4 engagement can result in the spontaneous loss of gp120, without infection, resulting in defective gp41 stumps." (PMID 23375046, 2013). "Thus, CD4+Foxp3+ Treg cells appear to be the predominant T-cell source of IL-10 at the infection site, whereas in the LN IL-10 also emanates from CD4+Foxp3− Teff cells." (PMID 23319295, 2013). "Although the acute phase of herpes virus infection can be controlled by redundant immune cell subsets involving CD8 T cells, B cell, and NK cells, CD4 T cells seem to have a crucial role in the establishment of viral latency and in the long-term control of the infection." (PMID 23717308, 2013). "Although this immune suppression is linked with a range of Th2 cell-extrinsic immune regulators, the fate of CD4+ Th2 cells during chronic infection, and the role of Th2 cell-intrinsic regulation in defining protective immunity to infection is largely unknown." (PMID 23516361, 2013). "Importantly, the production of IFN-γ and IL-17A by CD4+ T cells isolated from mice during the primary infection (3 dpi) was significantly lower than that observed upon re-challenge." (PMID 23853597, 2013). "Our studies revealed that the average infection frequency of lymph node derived memory CD4+ T-cells (250 cells per HIV DNA molecule, 0.4%) was 2–17 times higher but not significantly different from peripheral blood derived memory CD4+ T-cells (700 cells per HIV DNA molecule, 0.14%)." (PMID 23818847, 2013). "The results presented here now demonstrate that both UL138 and LUNA-specific CD4+ T cells also, themselves, secrete the immunomodulatory cytokine cIL-10, in direct contrast to CD4+ T cells specific for gB and IE antigens (which are expressed solely during lytic infection)." (PMID 24130479, 2013). "However, subsequent studies identified CD4+ Th1 cells as the primary cells involved in controlling infection." (PMID 24741372, 2013). "However, L13-Ia induced the expression of MHC class II, a phenomenon that allows IECs to stimulate CD4+ T cells during inflammation or in response to infection." (PMID 24365457, 2013). "Alongside the expected upregulation of ICOS by CD4+Foxp3− Teff cells during both infections, CD4+Foxp3+ Treg cells showed increased expression of ICOS over the first 4 weeks of H. polygyrus infection and during the acute egg phase (weeks 6–8) of S. mansoni infection." (PMID 23319295, 2013).
infection (continued). "Therefore, we determined the impact LAINefP72A/P75A infection in BLT mice on CD4+ T cells in bone marrow, lymph node, liver, lung and spleen." (PMID 24172637, 2013). "Moreover, recent human challenge studies suggest that CD4 T cell responses correlate well with outcome of infection and nearly all individuals have CD4 T cells specific for influenza viruses." (PMID 24155927, 2013). "Human colostrum and milk contain macrophages and DC that express DC-SIGN, which therefore could mediate HIV-1 trans infection of CD4+ T cells that are also present." (PMID 24278768, 2013). "Interestingly, the removal of HS or the use of heparin as a competing molecule reduced both HIV attachment and infection in several cell models such as CD4+ HeLa, T-cell lines and macrophages." (PMID 24116111, 2013). "However, at day 254 of infection, Mtb-specific IL-17A-producing CD4+ T cells were significantly enhanced in IL-22−/− mice." (PMID 23460846, 2013). "Early appearance of CD4 pre-memory T cells has also been demonstrated as early as day 3 post-infection in Listeria and in influenza infection by day 3.5; and phenotypic Tmem have been shown to be generated even in the presence of chronic viral and parasite infection." (PMID 24790593, 2013). "ZFNs that can disrupt the CXCR4 gene in CD4+ T-cells have also been developed and it has been demonstrated that they confer resistance to cells against the X4-tropic HIV-1 strains associated with late-stage infection." (PMID 23364195, 2013). "Therefore, we further analysed for CD4+Foxp3+ Tregs in the lungs and draining lymph nodes of pDC depleted and sham-treated mice after Cpn infection." (PMID 24386207, 2013). "DC-dependent HIV-1 trans infection of CD4+ T cells is an efficacious HIV dissemination mechanism that has been hypothesized to provide virus particles evasion from host innate and adaptive immune responses." (PMID 23593001, 2013). "This study expands our understanding of the hematopoietic activities of the CD137/CD137L system by demonstrating that reverse CD137L signaling initiated by CD137+, activated CD4+ T cells in hematopoietic progenitor cells not only drives myelopoiesis during infections but also in aging." (PMID 23945137, 2013). "In this context, LFA-1 also determines the preferential infection of memory CD4+ T cells by HIV-1." (PMID 24047317, 2013). "The 102 HIV-1-seropositive women studied had advanced infection (median CD4 count, 124 cells/μL)." (PMID 23734875, 2013). "Pre-exposure to α-CD169 nAb alone blocked virus capture and trans infection to autologous CD4+ T cells by immature and mature DCs, while α-DC-SIGN nAb alone had modest inhibitory effects in immature DCs and failed to block HIV-1 capture by mature DCs, consistent with previously published results." (PMID 23593001, 2013). "Decreased RT and integration of HIV-1 were seen in resting CD4+ T cells from controllers relative to those from uninfected subjects after ex vivo infection with replication-competent, Vif-positive laboratory strains of HIV-1 without spinoculation or activation." (PMID 24146808, 2013). "One of the 4 selected antigens is the DO serine protease HtrA, which is particularly unique in that it induces both high antibody titres and IFNγ+/CD4+ T cells during natural infection in human beings (Grifantini, personal communication) and during experimental infection in mice." (PMID 24009891, 2013). "As a population recalcitrant to SIV infection, DN T cells have the potential to contribute to the maintenance of an effective immune and may be evolution's answer to preserve helper T cell functions during a CD4 T cell depleting infection." (PMID 23825945, 2013). "However, upon infection the population of IL-21R−/− Treg cells expanded 3-fold over that of WT Treg cells to represent 30% versus 10% of all CD4+ T cells, respectively." (PMID 23696736, 2013).
infection (continued). "To better define the role of E2 in affecting viral entry, we pre-treated CD4+ T-cells and macrophages with E2 prior to infection with a single cycle, VSV-G pseudotyped virus, which enters the cells by endocytosis and bypasses receptor/coreceptor attachment and fusion." (PMID 23614015, 2013). "Additional studies in CD4 T-cell lines have provided evidence for silent integration leading to latency, sometimes by showing reactivation of latent virus as early as one day post-infection." (PMID 23375003, 2013). "Specific inhibitors of Akt would decrease productive infection, by favoring cell death during virus attachment to CD4+ CCR5+ target cells, and reduce immune activation to prevent Fas-dependent death of uninfected CXCR5+ PD-1+ CD4 T cells including T follicular helper cells that share this phenotype." (PMID 23742646, 2013). "Therefore, comparisons of CD4+ T-cell levels were assessed 4–12 weeks post-HIV-1NFNSX infection and 2–10 weeks post-HIV-1NL4-3 infection." (PMID 23300932, 2012). "Additionally, as our cultures can never be 100% pure, it is almost impossible to conclusively prove that any low level spreading infection results from resting cells instead of contaminating activated CD4+T cells." (PMID 22911005, 2012). "One key precondition for protective responses is expression of the respective Salmonella antigen during infection, and some data suggest that highly abundant antigens might be particularly well recognized by CD4 T cells." (PMID 23093937, 2012). "The repertoire of Salmonella epitopes recognized by CD4+ T cells during infection is largely unknown with the exception of epitopes in flagellin (FliC) and the type-III-secretion system." (PMID 22912884, 2012). "Indeed, one unique cluster contains the majority of long-term non-progressors, defined here as patients several years post infection with high CD4 nadir and low HIV viral load." (PMID 22860124, 2012). "Moreover, the percentage of EutC243–257-specific CD4+ T cells gradually increased until day 28 post-infection." (PMID 22912884, 2012). "Human immunodeficiency virus (HIV) and simian immunodeficiency virus (SIV) infections are characterized by continuous CD4+ T cell destruction, chronic immune activation and increased susceptibility to opportunistic infections that are easily controlled by healthy individuals." (PMID 22511950, 2012). "PBMCs infected with USA300, USA300Δhla, USA300Δhla comp, or USA300ΔsaeR/S for 6 hours then stained with PI and either anti-CD4 or anti-CD8 also demonstrated that Hla significantly contributes to T cell plasma membrane permeability during infection of PBMCs with USA300." (PMID 22574180, 2012). "Moreover, infection with Lm is mainly accompanied by undesired CD4+ T-cell mediated delayed type hypersensitivity (DTH) responses and granulomatous inflammation." (PMID 22536395, 2012). "This process requires HIV-1 binding to the DC surface, viral capture and release of trapped viruses at the infectious synapse, a cell-to-cell contact zone between uninfected DCs and interacting CD4+ T cells, which facilitates infection by locally concentrating virus and viral receptors." (PMID 23271952, 2012). "However, compared with B10.A mice, and at both post-infection periods, higher numbers of CD4+CD25+Foxp3+ Treg cells were found in A/J mice." (PMID 23226464, 2012). "Consequently, we analyzed individuals with longitudinal CD4 counts out to three-years post infection in order to determine if the observed early benefit was sustained in early chronic stages of infection." (PMID 23209412, 2012). "Notably, the lack of IL-10 significantly increased the frequency of IFN-γ+ CD8+ and CD4+ T cells in the lung on day 8 post infection, supporting the conclusion that IL-10 is important for dampening the activation of inflammatory T cells during RSV infection." (PMID 22393401, 2012).
infection (continued). "We then investigated the effect of HAART on the B cell compartment of a cohort of HIV-1-infected individuals who experienced low levels of CD4+ T cell counts during the course of infection (median nadir: 183 cell/μL), and maintained undetectable HIV-1 viral load for the last 12 months of therapy." (PMID 22474482, 2012). "In addition, CD4+ T cells isolated from day 5 post-infection from α-PD-L1-treated mice secreted more IFN-γ than did CD4+ T cells from control mice." (PMID 22319445, 2012). "However, the protective effects of IL-7 were not sustained after treatment interruption with both naïve and memory CD4+ T cells becoming significantly decreased, compared to baseline values, on day 62 post-infection, 4 weeks after the last injection of IL-7." (PMID 22511868, 2012). "Thus, we tested the ability of increasing concentrations of HD5 to inhibit infection by a primary HIV-1 isolate (HIV-1J176) in primary CD4+ T lymphocytes." (PMID 23028850, 2012). "However, within the group of individuals for whom CD4 cell counts prior to infection were known, we found that CD4 cell numbers prior to infection were elevated within the group of individuals carrying the HH genotype (p = 0.022)." (PMID 22412885, 2012). "Given that MDM utilize predominantly Trx during HIV-1 entry, the observed elevation of plasma Trx during chronic stages of HIV disease may enhance macrophage infection and help sustain high viremia even when very low levels of CD4+ T-cells exist." (PMID 23206338, 2012). "CD4+ T cells play a central coordinating role in the orchestration of adaptive immunity to infection, and may also mediate direct antiviral activity." (PMID 22589728, 2012). "To determine whether RA signaling was directly targeted to CD4+ T cells during infection, we measured CCR9 expression by T cells as a surrogate marker of RA activity." (PMID 22927819, 2012). "It is evident from studies over the years that direct infection is not sufficient to account for all the CD4 loss in HIV infections." (PMID 23202514, 2012). "In addition our results show that infection of primary naïve CD4+ T cells (low TGF-β1 expressing cells) with a constitutively active GLI2 lentivirus enhances TGF-β1 transcription." (PMID 22859956, 2012). "We observed a significant correlation between viral load and estimated SIV DNA half-life, suggesting that the high levels of infection and CD4+ T cell activation may play a role in determining SIV DNA turnover." (PMID 22496643, 2012). "Thus, the small amount of CXCR4-dependent infection seen in NP2/CD4/CXCR4 cells is likely due to the over-expression of this coreceptor and does not reflect CXCR4 use on primary cells." (PMID 22693444, 2012). "Finally, the absence of some cell populations of the immune system (e.g. igh6, IRF-2, Cd4 and Aβ) seems to favor the elimination of Brucella, a fact that suggests that some regulatory phenomena are induced during infection." (PMID 22500859, 2012). "Despite the advent of potent combinations of this therapy, the long-lived HIV-1 reservoirs like cells from monocyte-macrophage lineage and resting memory CD4+ T cells which are established early during primary infection constitute a major obstacle to virus eradication." (PMID 22548060, 2012). "Its concentration in CSF reflects local immune activation, a central aspect of HIV infection, and provides an index of progression across the entire disease spectrum, ranging from neuroasymptomatic infection with declining blood CD4+ T cell counts to HAD/HIVE, and with reduction in response to cART." (PMID 22433316, 2012). "In vivo T cell depletion experiments indicate that CD8+ T cells are essential for survival of GRA1-vaccinated C3H mice during acute phase of T. gondii infection, while depletion of CD4+ T cells led to an increase in brain cyst burden during the chronic phase of infection." (PMID 22837100, 2012).
infection (continued). "Although NL-DT5R established a productive infection and elicited humoral responses in PTMs, it did not cause CD4+ T-cells depletion or disease." (PMID 23336082, 2012). "Th1 CD4+ cells confer immunity to infection by intracellular pathogens through production of effector cytokines IFN-γ, Il-12, TNF, and IL-2, while Th2 CD4+ cells promote the clearance of multicellular helminths and ectoparasites by producing IL-4, IL-5 and IL-10." (PMID 22685452, 2012). "Pairwise comparisons of the CD4 count, antiretroviral therapy status, and the proportion of gp41 ambiguous base pairs within transmission pairs correlated with the reported order of infection events." (PMID 22615999, 2012). "However, by 6 weeks post-infection, there was a statistically significant difference in CD4 cell numbers and levels of infected cells between mice with cells expressing the HIV-specific TCR and mice with cells expressing the control TCR." (PMID 22511873, 2012). "Furthermore, the mean value (0.925 +/- 0.567) for cumulative CD4/CD8 T cell ratios from 2 to 112 weeks post infection for FIV-infected cats was significantly less than that for the FIV-uninfected cats (1.8113 +/- 0.412; p < .0001)." (PMID 22314004, 2012). "Interestingly, however, the characteristics of the virus-specific CD4 T cell and the B cell response to NC infection differed in DR1 and B10 mice." (PMID 22457834, 2012). "Mice with dominant negative MAML (DNMAML) protein preventing the canonical transcriptional activation by all four Notch receptors were previously reported to be able to control infection with L. major and to have normal levels of IFNγ in their dLN CD4+ T cells." (PMID 22396647, 2012). "In contrast, significant drop in the CD4+CD8− T cell frequency was observed in piglets which succumbed to the experimental infection, supporting the hypothesis that antibody development is the critical component of the protective immune response." (PMID 22303463, 2012). "Paradoxically, HIV-1 capture into mDCs appears to also critically enhance viral dissemination in lymphoid tissue by efficient release of infectious virus to CD4+ T cells in the DC-T-cell synapse, thus promoting pathogenesis and disease progression through trans-infection." (PMID 22545022, 2012). "CD4 is a single-membrane spanning protein, and HIV variants recognizing CD4 as the sole infection receptor have not been isolated." (PMID 23304142, 2012). "It has been reported that sCD4 can modestly enhance the infectivity of some HIV-1 strains at suboptimal concentrations in CD4-CCR5+ cells because sCD4 may efficiently replace CD4 on cell surface to drive infection of the CD4-negative and CCR5-positive cells." (PMID 23217195, 2012). "In addition, CXCR4-tropic (X4) virus HIV-1NL4-3 strongly depleted the central memory CD4+ T cell subset in the hNOK/B51Tg mice after an infection with HIV-1." (PMID 22880104, 2012). "Activated proliferating HIV-specific CD4+ T cells are detectable in early infection." (PMID 22754568, 2012). "In other words, if WT viral DNA is detected in resting CD4+ T cells during chronic infection and remains at similar levels when measured later, this supports low rates of turnover of viral DNA populations during active infection." (PMID 22496643, 2012). "In addition to this general role of Tregs in chronic viral infection, there is a unique role of Tregs in HTLV-1 infection due to direct infection of CD4 T cells by HTLV-1, which include both progenitor Treg cells and Treg cells." (PMID 23198153, 2012). "In addition, the binding between BSSL and CXCR4 should be further characterized including the effect of such binding on infection with CXCR4-using variants, CXCR4 signaling and CD4+ T-lymphocyte proliferation and migration." (PMID 22412885, 2012). "The lack of change in CD4− iNKT populations during in vitro infection suggests that loss of the CD4+ subset is not largely due to CD4 downregulation." (PMID 22916008, 2012).